ACACB (acetyl-CoA carboxylase beta)
Description:
Mitochondrial enzyme that catalyzes the carboxylation of acetyl-CoA to malonyl-CoA and plays a central role in fatty acid metabolism. Catalyzes a 2 steps reaction starting with the ATP-dependent carboxylation of the biotin carried by the biotin carboxyl carrier (BCC) domain followed by the transfer of the carboxyl group from carboxylated biotin to acetyl-CoA. Through the production of malonyl-CoA that allosterically inhibits carnitine palmitoyltransferase 1 at the mitochondria, negatively regulates fatty acid oxidation (By similarity). Together with its cytosolic isozyme ACACA, which is involved in de novo fatty acid biosynthesis, promotes lipid storage (By similarity).
Synonyms: ACC2; ACCB; HACC275; ACC-beta; ACCbeta; ACACbeta
Tractability: Small molecule: a drug acting on it is in phase 2 or 3 trials; a structure with a bound ligand is known; a high-quality ligand is known; it has a high-quality binding pocket; it belongs to a druggable protein family. PROTAC: ubiquitination databases record sites on it; its protein half-life has been measured; a small molecule that binds it is known.
Target class: Enzyme; Ligase
Chemical probes: CHEMBL3110081
Gene: Protein-coding gene on chromosome 12 (109,116,587 to 109,268,226, forward strand). Ensembl gene ENSG00000076555.
Subcellular location: Mitochondrion
Pathways (Reactome):
Metabolism: Activation of gene expression by SREBF (SREBP); Biotin transport and metabolism; Carnitine shuttle; ChREBP activates metabolic gene expression
Gene Ontology:
Molecular function: acetyl-CoA carboxylase activity; identical protein binding; protein binding; ATP binding; biotin binding; ligase activity; metal ion binding
Biological process: acetyl-CoA metabolic process; protein homotetramerization; fatty acid homeostasis; acyl-CoA metabolic process; D-glucose import across plasma membrane; energy homeostasis; fatty acid biosynthetic process; fatty acid oxidation; intracellular aspartate homeostasis; intracellular glutamate homeostasis; lactic acid secretion; malonyl-CoA biosynthetic process; negative regulation of fatty acid beta-oxidation; negative regulation of fatty acid oxidation; negative regulation of lipid catabolic process; pentose-phosphate shunt; positive regulation of heart growth; positive regulation of lipid storage; purine nucleotide metabolic process; regulation of cardiac muscle hypertrophy in response to stress; regulation of glucose metabolic process; response to nutrient; response to nutrient levels; response to xenobiotic stimulus; tricarboxylic acid metabolic process
Cellular component: mitochondrion; nucleus; cytosol; mitochondrial outer membrane; mitochondrial fatty acid beta-oxidation multienzyme complex
Genetic constraint (gnomAD): Loss-of-function variants: 198 observed, 264.12 expected, observed/expected ratio (o/e) 0.75, 90% interval 0.67 to 0.84. The upper end of that interval is the gene's LOEUF score, 0.84, which puts it in group 3 of 6, group 1 being the genes least tolerant of losing a copy. Missense variants: 2,695 observed, 3,175 expected, observed/expected ratio (o/e) 0.85, 90% interval 0.82 to 0.88. Synonymous variants: 1,097 observed, 1,250.4 expected, observed/expected ratio (o/e) 0.88, 90% interval 0.83 to 0.92.
Homologues: Orthologues: chimpanzee ACACB (99% identical), macaque ACACB (98% identical), dog ACACB (90% identical), mouse Acacb (88% identical), pig ACACB (88% identical), rat Acacb (88% identical), rabbit ACACB (87% identical), guinea pig ACACB (87% identical), tropical clawed frog acacb (77% identical), zebrafish acacb (72% identical), Drosophila melanogaster ACC (58% identical). Paralogues in human: ACACA (72% identical), PC (13% identical), MCCC1 (9% identical), PCCA (9% identical).
Diseases named in the same sentence as ACACB in open-access papers:
ACACB is named in the same sentence as 58 diseases in open-access papers, as found by Europe PMC text mining. Sharing a sentence is not in itself a finding about the gene and the disease. The quoted sentences say what the papers report.
Obesity (30 papers, 2011 to 2026). Accumulation of substantial excess body fat. "Research has shown that prevalent variants of the ACACB gene correlate with obesity and, separately, with type 2 diabetes in postmenopausal women, suggesting a critical function of acetyl-CoA carboxylase beta in these metabolic energy disorders." (PMID 39594522, 2024). "Acetyl-CoA carboxylase beta gene polymorphism (rs2268388, G > A) is associated with diabetes, diabetic nephropathy, insulin resistance, and obesity in some human populations." (PMID 37895167, 2023). "CPT1B and ACACB are genes related to fatty acid oxidation and are associated with obesity and diabetes." (PMID 34702302, 2021). "The current results reveal that ACACB SNP rs2268388 (reproducibly implicated in risk of nephropathy) associates with BMI in general populations and with obesity in subjects with T2D, as well as impacts gene expression in adipose and hepatic tissue." (PMID 23460794, 2013). "Higher ACACB expression is linked to obesity and insulin resistance in a mouse model fed a high-fat diet." (PMID 23460794, 2013). "Furthermore, in women with kidney disease and postmenopausal women, ACACB variants are associated with obesity and type II diabetes." (PMID 37895167, 2023). "Longitudinal intervention studies will assist in interpreting whether high ACACB expression is a risk factor for obesity and type 2 diabetes." (PMID 21887335, 2011). "Moreover, in ACACB knockout mice, continuous fatty acid oxidation increases insulin sensitivity, and feeding them a high fat/high carbohydrate diet is more likely to cause obesity and diabetes." (PMID 34573356, 2021). "ACACB has been reported in various diseases, including cancer, diabetic nephropathy, obesity, diabetes, and hepatic steatosis." (PMID 40084144, 2025). "ACACB knockout increased insulin sensitivity, mitigated high-fat-diet-induced obesity risks, and ameliorated hyperglycemia in mice." (PMID 40004488, 2025). "Acetyl-CoA carboxylase beta gene knockout mice have sustained fatty acid oxidation in the adipocytes, conferring protective effects against obesity and diabetes." (PMID 37895167, 2023). "Taken together, these studies suggest that the variability of ACACB regulates obesity and milk quality via fatty acid oxidation." (PMID 37895167, 2023). "ACACB is a biotin dependent enzyme which catalyzes irreversible carboxylation of acetyl CoA to manolyl CoA and is effective in obesity and diabetes by reducing fatty acids oxidation and increasing of insulin resistance." (PMID 36997916, 2023). "ACACB knockout mice have been shown to be protected from HFD-induced obesity and T2D through increased FA and glucose oxidation activity and increased lipolysis, thus promoting the maintenance of insulin sensitivity." (PMID 35159548, 2022). "Taken together, CD36, GLUL, COL4A2, and ACACB were considered as core genes in human adipose tissue with obesity or T2DM." (PMID 34085602, 2021). "ACACB has studied metabolic syndrome, obesity, colorectal cancer, diabetes diseases, lung cancer, and hepatocellular carcinoma." (PMID 34322485, 2021). "Taken together, CD36, COL4A2, GLUL, and ACACB were considered as core genes closely related to obesity and T2DM." (PMID 34085602, 2021). "ACACB inhibited fatty acid beta oxidation in the normal circumstances, expression of ACACB decreased in obesity and diabetes mice with the increase of time." (PMID 31805951, 2019). "ACACB is the key regulator of the fatty acid oxidation pathway and Acacb knock-out mice are reportedly protected against obesity and diabetes induced by high fat/high carbohydrate diets." (PMID 21887335, 2011). "It is conceivable that nutritional stress (e.g. diet-indued obesity and free fatty acid exposure) regulates ACACB expression." (PMID 21887335, 2011). "In addition, down- regulated of PTEN and ACACB genes can decrease blood sugar and subsequently prevent diabetes and obesity PTEN is a phosphatase which plays role in signaling pathway and suppression of tumor." (PMID 36997916, 2023).
Obesity (continued). "ACACB has been studied in metabolic syndrome, obesity, and diabetes-related diseases." (PMID 36111743, 2022). "ACACB variant rs2268388 was also associated with severe obesity in Spanish women, no data were provided in men." (PMID 23460794, 2013). "Although ACACB is a physiological candidate gene for obesity and diabetes, significant association has not been observed in GWAS." (PMID 23460794, 2013). "ACACB is also part of the adipocytokine signalling pathway and seems to play a central enzyme role in rats as well as in man and alterations of the expression pattern can possibly be responsible for obesity, diabetes, and other metabolic pathway activities." (PMID 21943323, 2011). "Some case reports also suggested that ACACB expression may be related to obesity." (PMID 34085602, 2021). "Animal studies suggest that the lack of strong association between ACACB variants and obesity/diabetes may be masked by the cross-regulation of ACACB expression and hormonal/nutritional status in insulin-sensitive tissues." (PMID 21887335, 2011). "Among those genes are insulin receptors, fatty acid synthase, lipoprotein lipase, adiponectin, leptin, acetyl-CoA carboxylase beta, and fatty acid binding protein 4 (FABP4), the latter being a new player connecting obesity with breast cancer development." (PMID 33801973, 2021). "On day 4, the network showed inhibition of the upstream regulator N-CoR in BPS-treated cells which leads to activation of adipogenic genes such as SCD, PLIN1, ACACB, CIDEC, ADIPOQ and FABP, leading to obesity." (PMID 27685785, 2016). "However, ACACB and HMGCR have been studied in metabolic syndrome, obesity, and tumors, and they have the function of promoting antitumor immunity." (PMID 36670748, 2023). "We anticipate identifying the genes closely related to obesity and T2DM and further investigate their relationship with the CD36, COL4A2, GLUL, and ACACB as they may be target genes for future therapies." (PMID 34085602, 2021). "Therefore, ACACB is variable and may play a vital role in the regulation of IMF and obesity." (PMID 37895167, 2023).
diabetes (17 papers, 2011 to 2025). "Finally, ACACB polymorphisms have been associated with diabetes mellitus, suggesting this gene is important in the regulation of metabolic disorders." (PMID 35406730, 2022). "ACACB may be involved in the regulation of fatty acid oxidation and associated with metabolic syndrome and diabetes." (PMID 31847222, 2019). "As a result, because the ACACB gene plays an important role in energy metabolism in the body, it might be proposed as a marker gene associated with childhood obesity and other metabolic disorders such as diabetes." (PMID 36200185, 2022). "Also, these compounds are able to downregulate some genes such as PTEN and ACACB which can protect against diabetes." (PMID 36200185, 2022). "The lack of association of ACACB variants with BMI/diabetes may also reflect the masking effect of gene*gene and gene*environment interactions." (PMID 21887335, 2011). "ACACB variants have not been shown to be associated with BMI or diabetes using GWAS." (PMID 21887335, 2011).
breast carcinoma (11 papers, 2013 to 2025). "Prior reviews have discussed correlations between the Adipocytokine signaling pathway (linked to HubGs CD36 and ACACB) and breast cancer cells, offering novel insights for prevention and treatment." (PMID 37893423, 2023). "In this study, we identified 8 cDEGs (COL11A1, COL10A1, CD36, ACACB, CD24, PLK1, UBE2C, and PDK4) as breast cancer (BC)-causing HubGs from 3 microarrays and one scRNA-seq dataset by the protein-protein interaction (PPI) network analysis of 46 cDEGs." (PMID 37893423, 2023). "ACACB served as an inhibitor of FA oxidation and studies showed that inhibition of ACACB reduced cell proliferation in breast carcinoma and hepatocellular carcinoma." (PMID 36478991, 2022). "Meanwhile, ACACB was served as a prognostic indicator in breast cancer patients receiving neoadjuvant chemotherapy." (PMID 34322485, 2021).
metabolic syndrome (11 papers, 2010 to 2023). A cluster of metabolic risk factors for CARDIOVASCULAR DISEASES and TYPE 2 DIABETES MELLITUS. "ACACB single nucleotide polymorphism (SNP) rs4766587 is associated with an increased risk of metabolic syndrome." (PMID 21887335, 2011). "Studies on fatty acid oxidation have reported that the allelic variants of human ACACB may be associated with metabolic syndrome." (PMID 37895167, 2023). "Since the presence of proteinuria is also recognized as a predictor of cardio-vascular diseases, the association of ACACB with proteinuria might reflect an association between the gene and cardio-vascular diseases or metabolic syndrome." (PMID 20168990, 2010). "The ACACB pathway may be a useful target for ameliorating metabolic syndrome." (PMID 23460794, 2013).
type 2 diabetes (10 papers, 2010 to 2026). "Acetyl coenzyme A carboxylase B gene (ACACB) single nucleotide polymorphism (SNP) rs2268388 is reproducibly associated with type 2 diabetes (T2DM)-associated nephropathy (DN)." (PMID 23460794, 2013). "In the present study, we showed ACACB located at chromosome 12q24.1 to be a strong susceptibility gene for diabetic nephropathy in patients with type 2 diabetes." (PMID 20168990, 2010). "In a large-scale association study of 1,312 Japanese subjects with type 2 diabetes using SNPs from a Japanese SNP database, we show that the T-allele of ACACB rs2268388 is associated with diabetic nephropathy." (PMID 20168990, 2010). "Subsequent replication studies in several different ethnic groups and a functional study suggest that the T-allele of a common intronic SNP (rs2268338) within ACACB is a risk factor for the development and progression of proteinuria in patients with type 2 diabetes." (PMID 20168990, 2010). "We hypothesize that higher expression of ACACB in the kidneys of subjects having the disease susceptibility allele (T) may increase the susceptibility to diabetic nephropathy in type 2 diabetes." (PMID 20168990, 2010). "Our findings suggest that a SNP within ACACB (rs2268388, intron 18 + 4139 C > T) contributes to the development of proteinuria in patients with type 2 diabetes." (PMID 20168990, 2010). "Interestingly, a common SNP rs2268388 within ACACB is reproducibly associated with type 2 diabetes-related proteinuria and end-stage renal disease in non-African American (AA) populations." (PMID 21887335, 2011). "Four core genes (COL4A2, ACACB, GLUL, and CD36) were found to be highly expressed in subcutaneous adipose tissue of obese patients accompanying type 2 diabetes." (PMID 34085602, 2021).
diabetic nephropathy (6 papers, 2010 to 2025). "In summary, based upon extensive genome-wide gene-centric SNP analyses, we identified ACACB as a candidate gene for conferring susceptibility to diabetic nephropathy." (PMID 20168990, 2010). "Therefore, we concluded that ACACB was likely a candidate for conferring susceptibility to diabetic nephropathy." (PMID 20168990, 2010). "Because the statistical power of this study for patients with type 1 diabetes was probably not sufficient, the association of variations in ACACB with diabetic nephropathy in patients with type 1 diabetes should be re-evaluated in future studies." (PMID 20168990, 2010). "However evidence suggesting a role for the ACACB in the pathogenesis of diabetic nephropathy was previously lacking." (PMID 20168990, 2010).
Insulin resistance (4 papers, 2011 to 2023). Increased resistance towards insulin, that is, diminished effectiveness of insulin in reducing blood glucose levels. "The CD36, GLUL, MYH11, CD163, and COL4A2 genes were closely associated with weight loss, while the ACACB gene was closely related to insulin resistance." (PMID 34085602, 2021). "Acacb knock-out mice and rats treated with Acaca or Acacb anti-sense nucleotide inhibitors suggested a potential therapeutic target for ACACB in insulin resistance, obesity, metabolic syndrome, and type 2 diabetes." (PMID 21887335, 2011).
Hepatic steatosis (3 papers, 2015 to 2025). Steatosis is a term used to denote lipid accumulation within hepatocytes. "Together, the overexpression of the three genes TENM2, GRIN2C, and ACACB in the CC group would indicate a greater synthesis of fats in the liver, which could lead to the accumulation of these and produce hepatic steatosis." (PMID 40160973, 2025).
hepatocellular carcinoma (3 papers, 2020 to 2022). A malignant tumor that arises from hepatocytes. "ACACB has been reported in laryngeal squamous cell carcinoma, nasopharyngeal carcinoma and hepatocellular carcinoma." (PMID 32299435, 2020).
Nephropathy (3 papers, 2013 to 2025). A nonspecific term referring to disease or damage of the kidneys. "The Aberrant expression of ACACB may induce renal lipid accumulation and metabolic dysregulation, further contributing to kidney damage." (PMID 40289841, 2025).
Biotin deficiency (2 papers, 2021). "ACACB is an enzyme that associated with diseases including Acetyl-Coa Carboxylase-Beta Deficiency and Biotin deficiency and it is related with the glucagon signalling pathway." (PMID 34085602, 2021).
liver cancer (2 papers, 2021 to 2022). An epithelial or non-epithelial malignant neoplasm that arises from the liver. "Decreased expression of ACACA or ACACB is associated with liver cancer suppression, as demonstrated in rats." (PMID 35159548, 2022). "ACACB is overexpressed in liver cancer and is highly associated with the prognosis." (PMID 34322485, 2021).
coronary artery disease (1 paper, 2017). "In conclusion, we discovered and confirmed a gain of the 10q24.31 (ERLIN1) and 12q24.11 (UNG, ACACB) genomic regions in patients with coronary artery disease and metabolic comorbidity." (PMID 28120895, 2017).
Ductal carcinoma in situ (1 paper, 2017). "We thus concluded that Five genes: CDK1, CCNB2, MAD2L1, PPARG, ACACB were finally identified to participate in the regulation and serve as potential diagnosis signatures in in Ductal carcinoma in situ." (PMID 28977921, 2017).
end-stage renal disease (1 paper, 2025). "Stratification analyses for microalbuminuria, macroalbuminuria and end-stage renal disease (ESRD) were also conducted for five variants: Ins/Del variant at ACE gene; SNP rs2268388 at ACACB gene; SNP rs1799987 at CCR5 gene; SNPs rs1800795 and rs1800796 at IL-6 gene." (PMID 40116328, 2025).
glaucoma (1 paper, 2023). Increased pressure in the eyeball due to obstruction of the outflow of aqueous humor. "Prioritized gene variants in our glaucoma case-control cohort supported possible causal roles in four genes for POAG (AQP5, FOXM1, SRFBP1 and CDH6) and three genes in PACG (LAMA2, ACACB and RGL3)." (PMID 36833422, 2023). "We identified rare, possibly pathogenic variations in AQP5, FOXM1, SRFBP1 and ACACB in the sporadic glaucoma cases that were not present in the families." (PMID 36833422, 2023). "Rare, deleterious SNVs in AQP5, SRFBP1, CDH6 and FOXM1 from POAG families and in ACACB, RGL3 and LAMA2 from PACG families were found exclusively in glaucoma cases." (PMID 36833422, 2023).
glioblastoma (1 paper, 2023). The most malignant astrocytic tumor (WHO grade IV). "Inhibiting ACACB has demonstrated a decrease in the proliferation and de novo lipogenesis of EGFRvIII human glioblastoma cells." (PMID 37660060, 2023).
glioma (1 paper, 2023). A benign or malignant brain and spinal cord tumor that arises from glial cells (astrocytes, oligodendrocytes, ependymal cells). "As shown in the LRS formula, the expression of GNAI3, ACACB, ADCY3, and ACADSB emerged as the most important LMRGs that contribute to the risk signature of gliomas patients." (PMID 36860853, 2023).
Hypercholesterolemia (1 paper, 2023). An increased concentration of cholesterol in the blood.